FMR1 (fragile X messenger ribonucleoprotein 1)
Diseases named in the same sentence as FMR1 in open-access papers (continued):
Sharing a sentence is not in itself a finding about the gene and the disease.
Fragile X-associated Primary Ovarian Insufficiency (17 papers, 2014 to 2025). "POI associated with the FMR1 gene premutation is referred to as Fragile X-associated primary ovarian insufficiency (FXPOI)." (PMID 38760837, 2024). "Fragile X-associated primary ovarian insufficiency (FXPOI) is due to an X-linked mutation that results from the expansion of a CGG repeat sequence located in the 5′ untranslated region of the FMR1 gene (premutation, PM)." (PMID 25147555, 2014). "Fragile X-associated primary ovarian insufficiency (FXPOI) is one of the disorders caused by the expansion of a CGG repeat sequence located in the 5′ untranslated region (UTR) of the X-linked FMR1 gene." (PMID 25147555, 2014). "Fragile X-associated primary ovarian insufficiency (FXPOI), characterized by amenorrhea before age 40 years, occurs in 20% of female FMR1 premutation carriers." (PMID 38760837, 2024). "Finally, and the central topic of this review, is the fragile X mental retardation 1 gene (FMR1), of which some specific alterations cause a particular form of POF, namely POF1 (formerly known as fragile X-associated primary ovarian insufficiency, or FXPOI)." (PMID 38275588, 2023).
tuberous sclerosis (16 papers, 2013 to 2025). Hereditary disease characterized by seizures, intellectual disability, developmental delay, and skin and ocular lesions. "Increased AKT/mTOR activity is consistent with deficiencies of FMR1, TSC1/2, or PTEN found in Fragile X, tuberous sclerosis, and Cowden syndrome." (PMID 33482199, 2021). "However, mutant models of Tuberous Sclerosis that exhibit hyperactive mTOR do not exhibit the same protein synthesis or mGluR-LTD phenotypes as seen in the Fmr1−/y model, and the role of this pathway in mGluR-LTD in WT is unclear." (PMID 35688821, 2022).
Alzheimer disease (13 papers, 2013 to 2026). A progressive, neurodegenerative disease characterized by loss of function and death of nerve cells in several areas of the brain leading to loss of cognitive function such as memory and language. "There is evidence for direct G-quadruplex role in regulated alternative splicing of fragile X mental retardation 1 (FMR1) transcripts and of beta-site amyloid precursor protein (APP) cleaving enzyme 1 (BACE1) involved in Alzheimer disease." (PMID 24040966, 2013). "However, previous case series have shown that FMR1 premutation carriers may have dual pathology on autopsy, specifically in cases of FXTAS and Alzheimer disease, and suggest that they may be synergistic in creating a worse neurological phenotype." (PMID 25368631, 2014).
amyotrophic lateral sclerosis (13 papers, 2012 to 2025). Amyotrophic lateral sclerosis (ALS) is a neurodegenerative disease characterized by progressive muscular paralysis reflecting degeneration of motor neurons in the primary motor cortex, corticospinal tracts, brainstem and spinal cord. "Another example is the amplification of RNA G4 repeats in amyotrophic lateral sclerosis/frontotemporal dementia (ALS/FTD) (C90RF72 gene) and Fragile X syndrome (FMR1 gene)." (PMID 38234925, 2023).
Autoimmunity (12 papers, 2010 to 2022). The occurrence of an immune reaction against the organism's own cells or tissues. "Increased rates of autoinflammatory and autoimmune disorders have been observed in female premutation carriers of CGG repeat expansion alleles of between 55–200 repeats in the fragile X mental retardation 1 (FMR1) gene." (PMID 24718368, 2014). "These varying mutations of the FMR1 gene have since also proven associated with risk towards autoimmunity and, potentially, BRCA1/BRCA2-associated cancer risks." (PMID 23948096, 2013). "This is, however, not the first observation where low and high sub-genotypes of the FMR1 gene denote opposing effects: het-norm/high was shown to be protective against autoimmunity, while het-norm/low promoted significant autoimmune risk." (PMID 22984553, 2012). "The FMR1 gene, mapping to an area of the X chromosome closely associated with autoimmunity also affects ovarian reserve, with specific genotypes associated with distinct ovarian aging patterns." (PMID 21526209, 2011). "We analyzed 339 consecutive IVF patients, 232 Caucasian, 59 African and 48 Asian, for FMR1 genotypes, and tested by multiple logistic regressions for associations between race/ethnicity, FMR1 genotype, autoimmunity and pregnancy chances with IVF." (PMID 21526209, 2011). "Logistic regression, with race/ethnicity and interaction between FMR1 genotype and autoimmunity in the model, has 2.5-times the odds of being associated with autoimmune positivity (OR 2.5, 1.34–4.55; P = 0.004)." (PMID 21526209, 2011). "At least in a genetically homogenous population of women with the het-norm/low FMR1 genotype, autoimmunity, indeed, appears negatively associated with pregnancy chances in IVF." (PMID 21179569, 2010). "This study, once again, reaffirms this by demonstrating a surprisingly close association between autoimmunity and the het-norm/low FMR1 genotype." (PMID 21179569, 2010). "In the thymus, we observed that FMR1 expression could be related to a predisposition to autoimmunity at two levels." (PMID 34789272, 2021). "Similarly, PCOS can be associated with autoimmunity, and with the previously noted low FMR1 alleles, by themselves associated with POS." (PMID 25906823, 2015). "Deficits in immune responses in female premutation carriers may lead to increased susceptibility to autoimmunity and further research is warranted to determine the link between FMR1 CGG repeat lengths and onset of autoinflammatory conditions." (PMID 24718368, 2014). "The association of FMR1 sub-genotypes and risk/protection for/from autoimmunity suggests that autoimmunity may be associated with lower pregnancy rates in IVF." (PMID 21526209, 2011). "Risk towards autoimmunity in all three races/ethnicities appears least affected with norm FMR1." (PMID 21526209, 2011). "A PCO-like phenotype with strongly associated autoimmunity and specific FMR1 genotype (het-norm/low), and the protective effect of another FMR1 genotype (het-norm/high), support the notion we made earlier that the FMR1 gene plays a role in regulating ovarian reserve." (PMID 21179569, 2010). "FMR1 sub-genotype het-norm/low is strongly associated with autoimmunity and decreased pregnancy chances in IVF, reaffirming the importance of the distal long arm of the X chromosome (FMR1 maps at Xq27.3) for autoimmunity, ovarian function and, likely, pregnancy chance with IVF." (PMID 21179569, 2010). "If autoimmunity was, however, assessed in reference to FMR1 genotype, the het-norm/low genotype was most frequently associated with autoimmunity (51.1%), followed by norm patients (38.3%) and het-norm/high women (24.2%), a statistically significant difference in distribution (p = 0.003)." (PMID 21179569, 2010). "Chromosomal abnormalities, FMR1 gene premutation, autoimmune disorders, ovarian surgery history, or chemo-/radiotherapy history was absent in any of the family members, and the mother had regular menses before the age of 50." (PMID 34868246, 2021).
Autoimmunity (continued). "There is clearly a link between FMR1 and autoimmunity depending on the number of upstream CGG triplets as observed in premutated carriers and FXPOI." (PMID 34789272, 2021). "In PCO patients with normal/low FMR1 genotype statistically, for example, higher rates of autoimmunity and lower pregnancy rates were detected." (PMID 29981579, 2018). "The specific reason why women with het-norm/low FMR1 convert so poorly is unknown but it is interesting to note that this sub-genotype is also highly associated with autoimmune risk, while its counterpart, the het-norm/high sub-genotype, is protective against autoimmunity." (PMID 23805952, 2013). "The interaction between FMR1 genotype and autoimmunity almost reached significance (P = 0.07), suggesting different FMR1 effects in races/ethnicities." (PMID 21526209, 2011). "Logistic regression with race/ethnicity and interaction between FMR1 genotype and autoimmunity in the model, demonstrated 2.5-times the odds of being associated with autoimmune positivity (OR 2.5, 1.34–4.55; P = 0.004)." (PMID 21526209, 2011). "This study, however, suggests that, at least in regards to autoimmunity, FMR1 gene effects vary between races/ethnicities." (PMID 21526209, 2011). "With the FMR1 gene mapping to Xq27.3, it appears to occupy the cross roads between ovarian function (ovarian recruitment and ovarian reserve) and autoimmunity." (PMID 21179569, 2010). "Here, we suggest for the first time another link between FMR1 and autoimmunity at the thymus level." (PMID 34789272, 2021). "Since higher prevalence of autoimmunity in women has remained unexplained, the FMR1 gene may have here an additional role to play." (PMID 22984553, 2012). "Moreover, logistic regression, with race/ethnicity and interaction between FMR1 genotype and autoimmunity in the model demonstrated 2.5-times the odds of being associated with autoimmunity." (PMID 21526209, 2011). "Our results suggest that FMR1 could play a central role in the thymus and autoimmunity." (PMID 34789272, 2021).
breast carcinoma (12 papers, 2013 to 2025). "Nevertheless, FMR1 is not only linked to breast cancer since its discovery but also in conjugation with other types of cancer." (PMID 32784829, 2020). "In contrast to these results however, overexpression of FMR1, which encodes fragile X mental retardation protein, has been associated with aggressiveness of breast cancer while its inhibition led to a reduction in invasiveness." (PMID 27448979, 2016). "In breast cancer, the analysis of four independent breast cancer datasets revealed that the overexpression of FMR1 mRNA, which codes for FMRP, is associated with an increased risk of lung metastasis formation, a correlation independent from the expression of estrogen receptor." (PMID 37379311, 2023). "Furthermore, high levels of FMR1 mRNA in human breast tissues are associated with breast cancer metastatic to lungs and with triple negative breast cancer (TNBC)." (PMID 24092663, 2013). "Interestingly, a similar result was reported in the Israeli study, where BRCA1/2 mutation carriers, a large majority of them already diagnosed with breast cancer, demonstrated only in 24.8% low FMR1 alleles, while random controls demonstrated low FMR1 alleles in 31.5% of women." (PMID 25036526, 2014). "The prognostic value of FMR1 was also determined for other cancers, such as esophageal squamous cell carcinoma, glioma, and aggressive breast cancer." (PMID 36133437, 2022). "FMR1 overexpression correlated with an increased probability of breast cancer progression, particularly metastasis to the lungs." (PMID 34044876, 2021). "We next analysed FMR1 mRNA expression on a large cohort of breast cancer patients recently made available by the Tumor Cancer Genome Atlas consortium (TCGA)." (PMID 24092663, 2013). "In addition, FMRP and FMR1 mRNA levels correlate with prognostic indicators of aggressive breast cancer, lung metastases probability, and triple negative breast cancer (TNBC)." (PMID 35351128, 2022). "Molecular and clinical evidence indicated that Fragile X Messenger Ribonucleoprotein 1 (FMRP) plays a role in different types of cancer, including breast cancer." (PMID 37379311, 2023). "FMR1, containing a CGG trinucleotide repeat element in its 5′ untranslated region, is highly expressed in human breast cancer and distal metastasis and affects cell-cell adhesion, cell shape and invasion of 4 T1 cell lines." (PMID 34044876, 2021). "We show here that FMRP and FMR1 mRNA levels correlate with prognostic indicators of aggressive breast cancer, lung metastases probability and triple negative breast cancer (TNBC)." (PMID 24092663, 2013).
Angelman syndrome (11 papers, 2012 to 2024). A neurogenetic disorder characterized by severe intellectual deficit and distinct facial dysmorphic features. "In previous studies, we found oromotor deficits in a Ube3a deficient mouse model of Angelman syndrome and in Fmr1 KO mice." (PMID 22984567, 2012). "Clinical labs already perform targeted testing for the FMR1 repeat expansion (FRAX, MIM 309548) and UPD 15 (Angelman syndrome, MIM 105830; Prader-Willi syndrome, MIM 176270) in such cases." (PMID 31694722, 2019). "Our data suggest that absence of Fmr1 does not affect intrinsic sensitivity of mesolimbic circuits to brain stimulation reward (BSR), which we have previously shown to be increased in mice lacking the maternal allele of ubiquitin ligase 3a (Ube3am-/p+), a model for Angelman syndrome." (PMID 24205018, 2013).
Obesity (10 papers, 2011 to 2025). Accumulation of substantial excess body fat. "Given that FMR1 gene mutations are associated with increased obesity, it is critical to examine FMR1 role in the regulation of energy balance." (PMID 37542065, 2023). "People affected with mutations in FMR1 have higher incidence of obesity, but the mechanisms are largely unknown." (PMID 37542065, 2023). "FMR1 mutations are associated with increased obesity particularly in children." (PMID 37542065, 2023). "Therefore, olfaction and alterations in activity of POMC neurons likely contribute to the dysregulation of energy balance and increased obesity in people affected with FMR1 mutations." (PMID 37542065, 2023). "Such is the case of FMR1 with its implication in developing obesity or NDvD." (PMID 32982666, 2020). "The reduced adiposity we observed in Fmr1-KO mice could at first sight be contradictory with the reports of hyperphagia and obesity in a rare subset of Fragile X patients displaying Prader Willi-like (PWL) phenotypes." (PMID 31632352, 2019). "Therefore, the use of new-targeted treatments in FXS has the potential to reverse or alleviate the obesity in affected individuals as it does in the FMR1 knockout (KO) mouse." (PMID 22043169, 2011). "The findings of a positive correlation of MMP-9 levels with obesity, CYFIP1 mRNA with mood and autistic symptoms, and FMR1 mRNA expression level with better cognitive, language, and adaptive functions indicate potential biomarkers for specific FXS phenotypes." (PMID 37508583, 2023). "Presently, a map of genes causing obesity in pleiotropic syndromes (SNRPN gene for the obesity in PWS, GNAS1 gene in PHP1A, ALMS1 gene in ALMS, FMR1 gene in FXS, and others), has been established." (PMID 25866584, 2015). "Individuals with large deletions affecting the FMR1 gene usually display typical features of FXS, including seizure and obesity and if the deletions span over adjacent genes, they may present with additional manifestations." (PMID 35646065, 2022).
Premature ovarian insufficiency (10 papers, 2018 to 2026). Amenorrhea due to loss of ovarian function before the age of 40. "The association between FMR1 gene premutation and premature ovarian insufficiency (POI) is well established." (PMID 39202368, 2024). "The aim of this study is to assess the association between the number of CGG repeats in FMR1 in Chinese patients with premature ovarian insufficiency (POI) and diminished ovarian reserve (DOR)." (PMID 32787884, 2020). "Premutations in FMR1 are the most common monogenic cause of premature ovarian insufficiency and are routinely tested for clinically; however, the mechanisms that contribute to the pathology are still largely unclear." (PMID 32777047, 2020). "Fragile X‐associated premature ovarian insufficiency (FXPOI) is among a family of disorders caused by expansion of a CGG trinucleotide repeat sequence located in the 5′ untranslated region (UTR) of the fragile X messenger ribonucleoprotein 1 (FMR1) gene on the X chromosome." (PMID 36250920, 2022). "In its premutated state (54–200 repeats), FMR1 contributes to the pathogenesis of premature ovarian insufficiency (POI)." (PMID 40244008, 2025). "In western countries, premutation of FMR1 are reportedly correlated with POI in women, which is now referred to as fragile-X-associated primary ovarian insufficiency (FXPOI)." (PMID 32787884, 2020). "The relationship between premature ovarian insufficiency (FXPOI) and premutation in the FMR1 gene is well established." (PMID 39202368, 2024).
Huntington disease (9 papers, 2011 to 2025). Huntington disease (HD) is a rare neurodegenerative disorder of the central nervous system characterized by unwanted choreatic movements, behavioral and psychiatric disturbances and dementia. "In a similar manner to Huntington’s disease (HD), FXS is caused by the expansion of a trinucleotide (CGG) repeat in the FMR1 gene located at the distal end of the long arm of the X chromosome (Xq27." (PMID 39336708, 2024). "The genetic diagnostics was performed which excluded spinocerebellar ataxia types 1, 2, 3, 6, and 17, Huntington's disease, and FMR1 premutation." (PMID 36816046, 2023).
myotonic dystrophy type 1 (9 papers, 2011 to 2024). Steinert disease, also known as myotonic dystrophy type 1, is a muscle disease characterized by myotonia and by multiorgan damage that combines various degrees of muscle weakness, arrhythmia and/or cardiac conduction disorders, cataract, endocrine damage, sleep disorders and baldness. "Lastly, both expansions in FMR1 and DM1 display maternal anticipation/expansion, giving rise to distinct phenotypes (namely, FXS in FMR1 and congenital myotonic dystrophy type 1 in DMPK) and to DNA hypermethylation." (PMID 37759552, 2023).
Friedreich ataxia (8 papers, 2014 to 2025). An inherited condition that affects the nervous system and causes movement problems. "Our study shows that RNA/DNA hybrids (R-loops) form on expanded repeats of endogenous FXN and FMR1 genes, associated with Friedreich ataxia and Fragile X (FXS) disorders, in patient cells." (PMID 24787137, 2014). "Furthermore, thousands of drugs have been tested on neurons from patients with Friedreich’s ataxia on the reactivation of the silenced Fmr1 gene, Niemann–Pick disease type C on lysosomal cholesterol accumulation, and PD on MEF2C activity." (PMID 35163606, 2022).
colorectal cancer (7 papers, 2022 to 2025). A primary or metastatic malignant neoplasm that affects the colon or rectum. "Of note, emerging evidence indicates that FMR1 is increased in multiple cancers, such as colorectal cancer and HCC." (PMID 40342419, 2025). "FMR1 overexpressed in colorectal cancer tissues and enhanced the proliferation and metastasis of tumors." (PMID 39582531, 2024). "The signature might provide five candidate targets (RBMX, FMR1, IGF2BP1, LRPPRC, YTHDC2) associated with specific clinical features, prognosis and improvement in immunotherapy for patients with colorectal cancer." (PMID 37194014, 2023). "In addition, FMR1 can promote the development of colorectal cancer cells by stabilizing EGFR mRNA." (PMID 37302999, 2023). "And FMRP (Protein of FMR1) binds RIPK1 mRNA, suggesting that FMRP acts as a regulator of necroptosis pathway through the surveillance of RIPK1 mRNA metabolism in colorectal cancer." (PMID 38020922, 2023). "To clarify the role of RBMX, FMR1, IGF2BP1, LRPPRC and YTHDC2, we analyzed the mRNA expression patterns in human colorectal cancer specimens." (PMID 37194014, 2023).